KRT37 (keratin 37)
Synonyms: K37; KRTHA7; HA7
Tractability: No criterion of Open Targets' tractability assessment is met for any kind of drug.
Gene: Protein-coding gene on chromosome 17 (41,420,547 to 41,424,585, reverse strand). Ensembl gene ENSG00000108417.
Pathways (Reactome):
Developmental Biology: Formation of the cornified envelope; Keratinization
Gene Ontology:
Molecular function: protein binding; structural constituent of skin epidermis; structural molecule activity
Biological process: epithelial cell differentiation; intermediate filament organization; morphogenesis of an epithelium
Cellular component: extracellular exosome; cytoskeleton; cytosol; keratin filament
Genetic constraint (gnomAD): Loss-of-function variants: 38 observed, 42.45 expected, observed/expected ratio (o/e) 0.9, 90% interval 0.69 to 1.17. The upper end of that interval is the gene's LOEUF score, 1.17, which puts it in group 5 of 6, group 1 being the genes least tolerant of losing a copy. Missense variants: 579 observed, 589.51 expected, observed/expected ratio (o/e) 0.98, 90% interval 0.92 to 1.05. Synonymous variants: 251 observed, 250.33 expected, observed/expected ratio (o/e) 1, 90% interval 0.9 to 1.11.
Homologues: Orthologues: chimpanzee KRT37 (98% identical), macaque KRT37 (96% identical), dog KRT38 (74% identical), dog KRT37 (73% identical). Paralogues in human: KRT38 (92% identical), KRT31 (54% identical), KRT35 (54% identical), KRT32 (53% identical), KRT33A (53% identical), KRT33B (53% identical), KRT36 (53% identical), KRT34 (52% identical), KRT40 (47% identical), KRT39 (47% identical), KRT15 (40% identical), KRT14 (39% identical), and 56 more.
Diseases named in the same sentence as KRT37 in open-access papers:
KRT37 is named in the same sentence as 12 diseases in open-access papers, as found by Europe PMC text mining. Sharing a sentence is not in itself a finding about the gene and the disease. The quoted sentences say what the papers report.
psoriasis (2 papers, 2019 to 2022). An autoimmune condition characterized by red, well-delineated plaques with silvery scales that are usually on the extensor surfaces and scalp. "KRT15, KRT24, KRT31, KRT37, KRT78 are differentially expressed in psoriasis, while KRT5 and KRT14 are specific for AD." (PMID 35874668, 2022).
cataract 1 (1 paper, 2023). "The KRT37 gene (17q21.2) encodes KRT37–Keratin 37 (449 amino acids; 49,747 Da), which is found in hair and nails, and whose defects are identified in multiple types of cataract 1 and mucinous neoplasms of the appendix." (PMID 37509254, 2023).
staphylococcus aureus infection (1 paper, 2023). An infectious process in which the bacteria Staphylococcus aureus is present. "KEGG pathway: The bar chart of the KEGG pathways related to the set of genes showed that most genes were involved in Staphylococcus aureus infection (KRT32, C3, KRT38, and KRT37) and the estrogen signaling pathway (KRT32, KRT38, and KRT37)." (PMID 37900279, 2023).
cancer (1 paper, 2023). A tumor composed of atypical neoplastic, often pleomorphic cells that invade other tissues. "In addition, the pharmacogenomic study of the DEPs in GSCA also showed that the downregulation of proteins such as PRDX4, GDI1, and YWHAE and the upregulation of proteins such as CLEC3B, KRT38, KRT37, and HNRNPCL1 were linked to higher sensitivity toward 30 pan-cancer CTRP drugs." (PMID 37900279, 2023).
tumor (1 paper, 2021). "GBM tumor levels of KRT37 are highly correlated with Treg infiltration." (PMID 34681642, 2021).
KRT37 also shares sentences with these, for which no sentence is quoted: infection (2 papers); influenza (2); allergic disease (1); asthma (1); dilated cardiomyopathies (1); glioma (1); iron deficiency (1).